ERO1A (endoplasmic reticulum oxidoreductase 1 alpha)
Diseases named in the same sentence as ERO1A in open-access papers (continued):
Sharing a sentence is not in itself a finding about the gene and the disease.
tumor (continued). "Disruption or knockdown of ERO1α leads to improperly folded VEGF-A, reduced secretion, and consequently, impaired angiogenesis, which translates to delayed tumor growth and limited vascular development." (PMID 41226317, 2025). "Their study also showed that overexpressing ERO1α increased VEGF-A secretion, further supporting its role in VEGF-A processing and tumor angiogenesis." (PMID 41226317, 2025). "Authors have also demonstrated that mice with overexpression of ERO1α had higher levels of PMN-MDSCs infiltration in spleen, bone marrow, peripheral blood and tumor compared to mice bearing mock tumors." (PMID 41226317, 2025). "We posit that the ERO1α/IL-6/STAT3/SLC7A11 pathway is critical for mTORC1-mediated ferroptosis resistance and tumor growth and that it can be targeted for the treatment of cancers associated with dysregulated mTORC1 signaling." (PMID 38610018, 2024). "The ERO1α/IL-6/STAT3/SLC7A11 pathway is crucial for mTORC1-mediated ferroptosis resistance and tumor growth, and combining ERO1α inhibition with ferroptosis inducers is a novel and effective treatment for mTORC1-related tumors." (PMID 38610018, 2024). "Depletion of ERO1A in both cell lines significantly (p < 0.05, ANOVA) inhibited tumor sphere formation." (PMID 39496753, 2024). "Our findings indicated that CD79A, COL5A1, ERO1A, and GJB2 were significantly overexpressed in tumor tissues compared to normal tissues, while CD101 and CPA3 showed more active expression in normal lung tissues, aligning with our prior analysis." (PMID 39850883, 2024). "Examining data via the LinkedOmics platform, ERO1A protein expression was high in LUAD compared to other indications and was found to be higher in tumor versus normal lung tissue." (PMID 39496753, 2024). "Overall, the mTORC1/ERO1α/IL-6/STAT3/SLC7A11 signaling cascade, which is also present in human cancer cells, plays a critical role in ferroptosis resistance and tumor progression." (PMID 38610018, 2024). "In this manuscript, we explore the relationship between ERO1A expression and the critical determinants of progression of EGFRMUT-LUAD, including colony and tumor sphere formation, spheroid growth, matrix secretion and sensitivity to EGFR inhibitors." (PMID 39496753, 2024). "We showed that co-treatment with ERO1α siRNAs and IKE suppressed PDX tumor growth much more potently than either treatment alone." (PMID 38610018, 2024). "Inhibition of ERO1a and IDO1 also resulted in identification of 203 and 65 more secreted proteins at D5 respectively, signifying their inhibition upregulated the tumor spheroid secretome." (PMID 38187398, 2023). "ERO1a and IDO1 independently shape the myeloid cell compartment, but their roles in modulating the tumor secretome within myeloid cell interactions are underexplored." (PMID 38187398, 2023). "For example, inhibition of ERO1A/IRE1α in tumors might have a synergetic anti-tumor effect with immune checkpoint blockade by turning the tumor immunogenic and removing immune-suppressive signals, thereby restoring the anti-tumor capacity of the T cells in tumor hosts." (PMID 37769655, 2023). "By targeting both ERO1a and IDO1, we harnessed their unique modulation potential offered on the myeloid cell compartment and the tumor secretome." (PMID 38187398, 2023). "In conclusion, our study provides evidence supporting the simultaneous targeting of ERO1a and IDO1 as a promising strategy for modulating the myeloid cell compartment and altering the tumor secretome in PDAC." (PMID 38187398, 2023). "Disruption of ERO1A impairs the balance between IRE1α and PERK signaling activities and triggers lethal UPR in ER-stressed tumor cells, thereby promoting host anti-tumor immunity via ICD." (PMID 37769655, 2023). "After normalizing for tumor weight, Ero1aKO tumors showed higher proportions of CD4+ T, CD8+ T, and NK cells, suggesting ERO1A impedes lymphocyte infiltration." (PMID 37769655, 2023).
tumor (continued). "To validate the tumor-promoting role of C4 cells, we chose the EMT marker LAMB3 and the C4 highly expressed gene ERO1A as surrogate markers." (PMID 36209225, 2022). "The expression and localisation of ERO1α and CA9 in tumour spheres during hypoxia were analysed by a tumour sphere formation assay." (PMID 31142270, 2019). "HCT116 cells were transplanted into nude mice to compare the localisation of ERO1α and CA9 in in vivo tumours." (PMID 31142270, 2019). "Our immunohistochemical studies with ERO1α, CA9, and pimonidazole (an exogenous marker typically used to detect chronic hypoxia in tumour xenografts) indicated that the distribution of pimonidazole and ERO1α were very similar." (PMID 31142270, 2019). "Furthermore, higher ERO1α levels were significantly associated with a higher presence of metastasis, suggesting that ERO1α upregulation may have contributed to HCC progression by promoting tumor metastasis." (PMID 30377291, 2018). "Other ER folding assistants able to modulate the properties of tumor tissue include protein disulfide isomerase (PDI), Ero1α and GRP94." (PMID 25386408, 2014). "They found that ERO1α was among the top 10 upregulated genes in MCF-7 and T47D mammospheres, suggesting that it may contribute to tumor resistance." (PMID 41226317, 2025). "We found that the regulation of ERO1α was sensitive to KYNU-induced changes in the redox environment, which stimulate the PERK-eIF2α-ATF4 pathway, promote oxidative folding, reduce the number of MFPs, and thereby maintain tumor survival and progression." (PMID 40616124, 2025). "Hypoxia, a hallmark feature of the TME, not only directly disrupts ER protein folding by inhibiting disulfide bond formation but also upregulates the expression of redox enzymes such as ERO1α through HIF-1α activation, thereby influencing tumor angiogenesis and immune evasion." (PMID 41407677, 2025). "In vivo, 2′,4′-DHC suppressed tumor growth and enhanced oxaliplatin efficacy without systemic toxicity, highlighting the translational promise of combining ERO1α inhibition with ferroptosis inducers and chemotherapy." (PMID 41226317, 2025). "Despite growing evidence of its tumor-promoting functions, no clinically approved ERO1α inhibitors exist." (PMID 41226317, 2025). "Rather than acting through a single dominant pathway, ERO1α influences a range of interconnected mechanisms that support tumor survival, immune evasion, and treatment resistance." (PMID 41226317, 2025). "ERO1A aids protein folding by acting as a protein disulfide oxidase, and under cancer-related hypoxia conditions, it favors the folding of angiogenic VEGFA, leading tumor cells to thrive and spread." (PMID 39962052, 2025). "Their immunohistochemical analysis showed that tumor cells expressed ERO1α, while normal tissues did not." (PMID 41226317, 2025). "Similar to GSK2606414, an ERO1α (a PERK axis target gene) inhibitor also promoted CD8+ T-cell immunity, controlled tumour progression, and improved the immunotherapy response in mouse tumour models." (PMID 38297380, 2024). "Considering that PDO and PDX tumor models can highly preserve the heterogeneity and histological characteristics of the original tumors, we further tested the therapeutic potential of combining ERO1α inhibition and IKE in tumor treatment using PDO and PDX models." (PMID 38610018, 2024). "ERO1A can reshape TME to drive sustained immunosuppression maintained by endoplasmic reticulum stress response, thereby influencing the immune environment and response to PD-1 blockade, contributing to tumor survival." (PMID 39165641, 2024). "In addition, ERO1A, PKP2, and MERTK have been proved to promote the progress and drug resistance of NSCLC by enhancing the activation of tumor and PI3K, EGFR, and other signal pathways." (PMID 37101691, 2023).
tumor (continued). "The tumor center was characterized by a higher abundance of transferrin (TF), endoplasmic reticulum oxidoreductase 1 (ERO1)-like protein (ERO1A), EH domain-containing protein 1 (EHD1), keratin 5 (KRT5), serpin H1 protein (SERPINH1), and lactate dehydrogenase A (LDHA)." (PMID 35512017, 2022). "Thus, in this study, we focused on endoplasmic reticulum disulphide oxidase 1α (ERO1α), a protein that localises in the endoplasmic reticulum and is involved in the formation of disulphide bonds in proteins, to determine whether it could serve as a potential tumour-hypoxia biomarker." (PMID 31142270, 2019). "When assessed in fluorescence-based DCDFA assays, we observed that PDA cells lacking ERO1α displayed substantially reduced ability to generate ROS, exhibiting only 66% of the ROS capacity detected in WT tumor cells." (PMID 31666928, 2019). "Finally, we used a mouse model to investigate the localisation of ERO1α and CA9 in tumour xenografts using several cell lines." (PMID 31142270, 2019). "Given that ERO1α partners with PDI to carry out redox reactions in the ER lumen, we hypothesized that the newly discovered PDI inhibitor E64FC26 may shape T cell tumor control." (PMID 31779147, 2019). "Typically, ERO1α-positive staining was observed in HCC tumor tissues with ERO1α-negative or weak staining in adjacent nontumor tissues from patients with HCC." (PMID 30377291, 2018). "To explore the function of ERO1α in HCC development, we investigated levels of ERO1α mRNA and protein in tumor tissues and matched adjacent nontumor tissues from 114 patients with HCC." (PMID 30377291, 2018). "We observed higher ERO1α mRNA and protein levels in tumor tissues compared with adjacent nontumor tissues." (PMID 30377291, 2018). "Increased expression of Ero1α has been also previously shown for breast and various gastrointestinal cancer, with expression levels correlating with tumor growth and metastasis thus being probably involved in HCV-induced carcinogenesis and tumor progression." (PMID 26035647, 2015). "It has not been determined whether high expression of ERO1α in cancer directly promotes tumor progression or is merely a marker of changes in the tumor microenvironment." (PMID 41333024, 2025). "Extensive in vitro and in vivo experiments were carried out to determine the role of ERO1α and its downstream target, member 11 of the solute carrier family 7 (SLC7A11), in mTORC1-mediated cell proliferation, angiogenesis, ferroptosis resistance, and tumor growth." (PMID 38610018, 2024). "Mechanistically, ERO1A ablation impairs the balance between IRE1α and PERK signaling activities and induces lethal unfolded protein responses in tumor cells undergoing endoplasmic reticulum stress, thereby enhancing anti-tumor immunity via immunogenic cell death." (PMID 37769655, 2023). "We show that depletion of ERO1A in tumor cells may not be able to resolve ER stress due to impaired activation of the IRE1α pathway, resulting in an imbalance between IRE1α activity and PERK activation, which governs cell fate." (PMID 37769655, 2023). "Given that ERO1α function appears less critical under steady-state conditions, it is also possible that therapeutic disruption of this enzyme may succeed in limiting tumor growth and metastasis without significantly damaging healthy cells and tissues." (PMID 31666928, 2019). "Consequently, we believe that CA9 is not an optimal marker for the detection of tumour hypoxia, an important factor in cancer progression, while ERO1α can be a true hypoxic marker." (PMID 31142270, 2019). "Therefore it is not surprising, that mice with Ero1α knock-out are characterized by slower tumor growth." (PMID 29673197, 2018). "Although Ero1α is secreted from hypoxic tumor cells, we currently do not known whether this occurs in vivo and what the function of surface or extracellular Ero1α is." (PMID 25386408, 2014).
tumor (continued). "Thus, ERO1A-disrupted tumor cells may not be able to resolve the ER stress due to impaired activation of the IRE1α pathway, resulting in an imbalance between the IRE1α activity and PERK activation that governs cell fate." (PMID 37769655, 2023). "Hence, we concluded a novel molecular mechanism in which ERO1α promoted the metastasis and angiogenesis of HCC through S1PR1/STAT3/VEGF-A signaling, suggesting that reagents targeting the pathway would be beneficial for inhibiting tumor metastasis and angiogenesis." (PMID 30377291, 2018). "Without ERO1α, VEGF-A maturation is disrupted, reducing its ability to promote angiogenesis, leading to slower tumor growth and decreased metastatic potential." (PMID 41226317, 2025).
cancer (44 papers, 2015 to 2026). A tumor composed of atypical neoplastic, often pleomorphic cells that invade other tissues. "Beyond its established role in cancer, ERO1α is critically implicated in the pathogenesis of neurodegenerative diseases, aging, and hereditary myopathies, primarily through mechanisms of oxidative proteostasis." (PMID 41333024, 2025). "The formation of functional disulfides and the consequent secretion of VEGF121 was impaired in ERO1A-deficient cancer cells." (PMID 39962052, 2025). "ERO1α plays a crucial role in maintaining redox balance within the endoplasmic reticulum, yet its dysregulation in cancer has been associated with increased oxidative stress and alterations in cellular metabolism." (PMID 41226317, 2025). "The expression of ERO1α is significantly upregulated in a variety of cancers and associated with poor prognosis." (PMID 41333024, 2025). "The mechanism underpinning the dependency of cancer cells on ERO1A expression appears to be multifactorial, with the cause and effect of downstream targets mediating the observed phenotype not fully elucidated." (PMID 39496753, 2024). "Endoplasmic reticulum oxidoreductase 1 alpha (ERO1α), an ER-resident thiol oxidoreductase, is confirmed to be highly upregulated in various cancer types and associated with a significantly worse prognosis." (PMID 38454454, 2024). "ERO1A-deficient mice are viable, indicating that ERO1A targeting has potential efficacy for the treatment of cancer, which is further strengthened by the relatively mild phenotype associated with ERO1A KO mice." (PMID 39496753, 2024). "Previous studies have implicated ERO1α in a range of different cancer types, with current evidence suggesting potential roles in cancer cell invasion of healthy tissues, acquisition of chemoresistant properties, and promotion of angiogenesis." (PMID 31666928, 2019). "To uncover the importance of ERO1α expression in cancer biology and the molecular mechanisms underlying its protein functions, we generated conventional ERO1α KO clones and used the clones to perform mechanistic analyses." (PMID 28839225, 2017). "ERO1α can also be used as a new endogenous marker of chronic hypoxia, more reliable than carbonic anhydrase 9, a diagnostic biomarker and therapeutic target for cancer." (PMID 41333024, 2025). "These are just a few examples of many that ERO1α is associated with cancer indications." (PMID 33615311, 2020). "Collectively, the findings of this study involving a gene-modification approach indicate that ERO1α is a major proliferation-enhancing factor in cancer cells and could be used as both a diagnostic biomarker of cancer exacerbation and a therapeutic target." (PMID 28839225, 2017). "Because of the high ERO1A expression levels in aggressive TNBC and the limited therapeutic option of this cancer type, we investigated ERO1A selective inhibition there." (PMID 39962052, 2025). "Several studies have demonstrated that ERO1α plays a crucial role in the hypoxic response of cancer, particularly in regulating protein folding, angiogenesis, and adaptation to low-oxygen environments." (PMID 41226317, 2025). "The upregulation of ERO1A in cancer cells, oppositely to the dispensability of ERO1A activity in healthy cells, renders ERO1A a perfect target for cancer therapy." (PMID 39962052, 2025). "The potential of ERO1α as a predictive and prognostic biomarker in cancer requires further validation and methodological standardization." (PMID 41333024, 2025). "In summary, ERO1α plays an important role in the occurrence and development of cardiovascular diseases, cancer, neurodegenerative diseases and other diseases." (PMID 41333024, 2025). "In their respective studies, both Kutomi (2013) and Tanaka (2015) demonstrated that ERO1α levels rise under low-oxygen conditions in various cancer cell lines, including MCF-7, 4T1, and HeLa cells." (PMID 41226317, 2025).